GPR21 (G protein-coupled receptor 21)
Description:
Orphan receptor.
Tractability: Small molecule: it belongs to a druggable protein family. Antibody: UniProt places it where antibodies can reach, with medium confidence; UniProt predicts a signal peptide or a membrane-spanning region; its Gene Ontology location is reachable by antibodies, with medium confidence.
Target class: Family A G protein-coupled receptor; Membrane receptor
Gene: Protein-coding gene on chromosome 9 (123,033,667 to 123,035,665, forward strand). Ensembl gene ENSG00000188394.
Subcellular location: Cell membrane
Gene Ontology:
Molecular function: protein binding; G protein-coupled receptor activity
Biological process: G protein-coupled receptor signaling pathway
Cellular component: plasma membrane; membrane
Genetic constraint (gnomAD): Loss-of-function variants: 8 observed, 22.54 expected, observed/expected ratio (o/e) 0.35, 90% interval 0.21 to 0.64. The upper end of that interval is the gene's LOEUF score, 0.64, which puts it in group 2 of 6, group 1 being the genes least tolerant of losing a copy. Missense variants: 409 observed, 442.26 expected, observed/expected ratio (o/e) 0.92, 90% interval 0.85 to 1. Synonymous variants: 166 observed, 165.27 expected, observed/expected ratio (o/e) 1, 90% interval 0.88 to 1.14.
Homologues: Orthologues: dog GPR21 (95% identical), mouse Gpr21 (91% identical), rat Gpr21 (90% identical), tropical clawed frog gpr21 (73% identical). Paralogues in human: GPR52 (67% identical), CHRM3 (23% identical), CHRM5 (22% identical), HTR4 (21% identical), CHRM2 (21% identical), DRD5 (21% identical), HRH2 (21% identical), DRD1 (21% identical), CHRM1 (20% identical), TAAR9 (20% identical), DRD4 (20% identical), TAAR1 (20% identical), and 13 more.
Diseases named in the same sentence as GPR21 in open-access papers:
GPR21 is named in the same sentence as 10 diseases in open-access papers, as found by Europe PMC text mining. Sharing a sentence is not in itself a finding about the gene and the disease. The quoted sentences say what the papers report.
Obesity (7 papers, 2014 to 2023). Accumulation of substantial excess body fat. "GPR21 knockout mice are resistant to diet‐induced obesity with higher glucose metabolism and insulin sensitivity." (PMID 36721851, 2023). "In fact, GPR21 has been suggested to play a role in affecting body weight, insulin sensitivity, and glucose tolerance as GPR21 KO mice have improved insulin response and are protected from obesity." (PMID 35054972, 2022). "TheseGpr21 KO mice were leaner than their wildtype littermate control (Osbornet al.) and were resistant to diet-induced obesity (Gardneret al., 2012), making GPR21 a potential drug target candidate for the treatment of diabetes and obesity." (PMID 27081476, 2016). "Obesity-induced type 2 diabetes may be associated with the dysregulation of GPR21 through an increase in receptor expression, an increase in an endogenous agonist or a reduction in an inverse agonist, leading to the stimulation of the MAPKs, which contribute to the inhibitory influences of GPR21." (PMID 27243589, 2016). "The Gpr21 gene is widely expressed and has been shown to possess critical function in coordinating macrophage proinflammatory activity in the context of obesity-induced insulin resistance." (PMID 25296178, 2014). "GPR21 expression is associated with developing type 2 diabetes (T2DM), a multifactorial metabolic disease caused by pancreatic β‐cell dysfunction, decreasing insulin production, insulin resistance, and obesity." (PMID 36721851, 2023). "It has been suggested that GPR21 may coordinate macrophage pro-inflammatory activity and other cells such as adipocytes when there is obesity-induced insulin resistance." (PMID 36362842, 2022). "Analysis of the epididymal fat pads of wild type C57BL/6J mice, a meaningful indicator of obesity-related diabetes, revealed an increase in GPR21 expression, which trended towards significance, in HFHS-fed mice, with a concurrent elevation in the macrophage marker F4/80." (PMID 27243589, 2016). "For obesity‐induced T2DM, several class A orphan GPCRs, including GPR21, GPR35, GPR84, and GPR132, are suggested to play an active role in the developmental processes of T2DM." (PMID 36721851, 2023).
Insulin resistance (5 papers, 2014 to 2023). Increased resistance towards insulin, that is, diminished effectiveness of insulin in reducing blood glucose levels. "Overexpression of GPR21 in vitro has assisted in elucidating the underlying mechanisms by which this receptor may contribute to the development of insulin resistance and type 2 diabetes." (PMID 27243589, 2016). "This study focused on the orphan receptor, GPR21, which previous results have suggested is involved in the pathogenesis of insulin resistance, showing for the first time the presence of this receptor in HepG2 cells, and confirming its constitutive activity." (PMID 34639123, 2021). "Subsequently, we showed that GPR21 overexpression in HEK293T cells was associated with impaired insulin signalling, thus indicating a direct involvement in the establishment of insulin resistance." (PMID 34639123, 2021). "Interestingly, GPR21 has been shown to be involved in the pathogenesis of insulin resistance, thus representing a potential new target for the treatment of type 2 diabetes and metabolic syndrome." (PMID 36362842, 2022). "Targeting GPR21 with an inverse agonist such as the one identified in this study could curtail some of the many facets contributing to the development of insulin resistance and type 2 diabetes." (PMID 27243589, 2016). "In conclusion, we have shown that GPR21 negatively affects insulin sensitivity in hepatocytes, suggesting that its inhibition might represent a novel and promising pharmacological strategy to counteract the development of insulin resistance." (PMID 34639123, 2021).
type 2 diabetes (4 papers, 2016 to 2025). "Aligned with our findings, GPR21, which also had binding sites associated with the transcription factors, is expressively associated with developing type 2 diabetes, and it is a potential therapeutic target for its treatment." (PMID 40243421, 2025). "It is established that GPR21 is implicated in type 2 diabetes by Gαq signaling pathways." (PMID 36721851, 2023). "GPR21 belongs to class A orphan GPCR and is a novel treatment target for type 2 diabetes, primarily caused by systemic insulin resistance." (PMID 36721851, 2023). "Hence, the functional impact of GPR21‐mediated Gαs activation in type 2 diabetes warrants further investigation." (PMID 36721851, 2023). "Overall, these findings suggest that GPR21 could be a novel target for type 2 diabetes and other metabolic disorders." (PMID 36639690, 2023). "This work demonstrates the potential role GPR21 may play in the development of type 2 diabetes." (PMID 27243589, 2016). "Given the influence of GPR21 on insulin signalling, a molecule that blocks its constitutive activity in a similar manner to the prospective native ligand could be a novel and powerful pharmacological strategy for the treatment of type 2 diabetes." (PMID 27243589, 2016). "GPR21 is a class-A orphan G protein-coupled receptor (GPCR) and a potential therapeutic target for type 2 diabetes and other metabolic disorders." (PMID 36639690, 2023).
albinism (1 paper, 2017). A congenital disorder characterized by partial or complete absence of melanin pigment in the eyes, hair, or skin. "Although no differential expression of GPR143 was observed as in mammals’ albinism, the identification of other G-protein coupled receptor including GPR21 and GPR61 may imply their possible involvement in fish albinism." (PMID 28777813, 2017).
Huntington disease (1 paper, 2023). Huntington disease (HD) is a rare neurodegenerative disorder of the central nervous system characterized by unwanted choreatic movements, behavioral and psychiatric disturbances and dementia. "Although ECL2 is an effective self‐modulator on GPR21/52 activity, it has been shown that therapeutic modulation via the remote allosteric site is still a feasible approach in treating Huntington's disease and psychiatric disorders." (PMID 36721851, 2023).
metabolic disease (2 papers, 2023). A congenital disorder (due to inherited enzyme abnormality) or acquired (due to failure of a metabolically important organ) disorder resulting from an abnormal metabolic process. "In this work, the authors report Cryo-EM structures of the signaling complexes of human GPR21, an orphan GPCR and a potential metabolic disease target, and reveal unique receptor activation conformation when bound to downstream signaling proteins in the absence of any ligand." (PMID 36639690, 2023).
GPR21 also shares sentences with these, for which no sentence is quoted: diabetes (2 papers); metabolic syndrome (2); glioma (1); psychiatric disorder (1).